VWF (von Willebrand factor)
Diseases named in the same sentence as VWF in open-access papers (continued):
Sharing a sentence is not in itself a finding about the gene and the disease.
epistaxis (5 papers, 2013 to 2023). Bleeding from the nose. "With a decrease in vWF, the patient repeatedly suffered from epistaxis and bleeding from the surgical wound or slight abrasion." (PMID 33496866, 2021). "Patient 8 had normal VWF:Ag and VWF:RCo levels (55 and 61 IU/dL), but she had familial history of menorrhagia, epistaxis, and a pathological curve with ristocetin in the platelet aggregation study." (PMID 24385781, 2013). "Conveying these findings to patients bitten by B. jararaca, consumption and proteolysis of VWF by botrocetin and SVMP, respectively, seem to contribute to the manifestation of bleedings, particularly those from mucosae (gingival bleeding, hematuria, and epistaxis)." (PMID 34478462, 2021).
gastric adenocarcinoma (5 papers, 2018 to 2024). "Cancer-derived VWF enhances gastric adenocarcinoma metastasis through experiments in vivo and in vitro." (PMID 36105100, 2022). "The plasma levels of vWF antigen were 12.92 μg/mL, 15.29 μg/mL, and 18.84 μg/mL for healthy controls, patients with intraepithelial neoplasia, and patients with gastric adenocarcinoma." (PMID 29362409, 2018). "Consistently with findings in patients, vWF was detected in cells from the human gastric adenocarcinoma lines BGC823 and MKN45." (PMID 29362409, 2018). "Immunocytochemistry detected vWF both in endothelial cells and in the gastric adenocarcinoma cells from all 94 patients with adenocarcinoma, as compared to exclusive vWF staining in endothelial cells of normal gland cells." (PMID 29362409, 2018). "Patients with poorly differentiated gastric adenocarcinoma had the highest levels of plasma vWF." (PMID 29362409, 2018).
hemolytic-uremic syndrome (5 papers, 2015 to 2023). Acute kidney injury associated with microangiopathic hemolytic anemia and thrombocytopenia. "As an example, VWF is a predictor for pulmonary involvement in patients with systemic sclerosis, while the levels of VWF correlate with disease activity in connective tissue disorders and hemolytic/uremic syndrome." (PMID 36765638, 2023).
hemorrhagic stroke (5 papers, 2020 to 2025). A stroke caused by a bleed on the brain. "Hemorrhagic stroke risk differed significantly in both the VWF:Act/Ag and VWF:CB/Ag strata (log-rank: p = 0.01 and 0.005, respectively)." (PMID 38896804, 2025). "Gastrointestinal bleeding and hemorrhagic stroke events occurred significantly more in patients with VWF:CB/Ag and VWF:Act/Ag ratios ≤0.7 observed in the early postoperative phase (<60 days)." (PMID 38896804, 2025). "Patients experiencing GIB or hemorrhagic stroke events had a median VWF:Act/Ag ratio of 0.63 (IQR: 0.58–0.68) and VWF:CB/Ag ratio of 0.62 (IQR: 0.56–0.67), respectively, after stabilization." (PMID 38896804, 2025). "Using brain tissues from a hemorrhagic stroke patient, M4M was found partly localized with neuronal marker NeuN and vascular endothelial marker vWF." (PMID 34002002, 2021). "In patients with VWF:CB/Ag and VWF:Act/Ag ratios ≤0.7 observed in the early postoperative phase, more GIB and hemorrhagic stroke events were observed during long-term LVAD support." (PMID 38896804, 2025). "For example, studies have reported that intraventricular administration of VWF leads to increased BBB permeability and that ADAMTS13 blocked BBB opening in both ischemic and hemorrhagic stroke mice." (PMID 32075652, 2020).
Hypofibrinogenemia (5 papers, 2021 to 2024). Decreased concentration of fibrinogen in the blood. "Cryoprecipitate, containing Factor VIII, Factor XIII, von Willebrand Factor, fibrinogen, and fibronectin, is primarily used to treat acquired hypofibrinogenemia in cardiac surgery." (PMID 39081365, 2024). "Prothrombin complex concentrate (PCC), fibrinogen concentrates, or cryoprecipitates (containing fibrinogen, von Willebrand Factor, and Factor VIII) are preferred because they balance the hypofibrinogenemia with less volume overload." (PMID 36676081, 2023). "Our testing could not determine the relative contribution of hypofibrinogenemia, anti-platelet medication, intrinsic platelet dysfunction, and abnormal vWF on the abnormal clot strength." (PMID 33846433, 2021).
Hypoglycemia (5 papers, 2021 to 2026). A decreased concentration of glucose in the blood. "Hypoglycemia induces the release of von Willebrand Factor (vWF) from endothelial cells and platelets, and vWF, in turn, promotes platelet aggregation and prolongs the lifetime of factor VIII." (PMID 37298308, 2023). "Mild prolonged hypoglycemia increased the %change of the following protein in control subjects: vWF (139.5 ± 79.0 vs. 41.2 ± 18.0%change at hypoglycemia, study-1 vs. study-2, p = 0.03)." (PMID 36203210, 2022). "By 24-hours, in controls, Protein S continued to show increased %change in response to deep-hypo and vWF continued to show increased %change in mild-hypo; plasminogen emerged at this timepoint as showing increased %change in milder prolonged hypoglycemia." (PMID 36203210, 2022). "A similarly high %change of vWF was observed in mild-hypo compared to deep-hypo in T2D (112.3 ± 77.1 vs. 17.7 ± 13.0%change of vWF at 24 h post-hypoglycemia, study-1 vs. study-2, p = 0.05)." (PMID 36203210, 2022). "By 24-hours, in T2D, CD40LG continued to show increased %change in milder prolonged hypoglycemia; vWF emerged at this timepoint similarly showing increased %change in milder prolonged hypoglycemia." (PMID 36203210, 2022). "From baseline to hypoglycemia, %change differences between studies were seen in PRPs for both T2D (PAI-1, CD40LG, GPVI, tissue factor) and controls (PAI-1, CD40LG, Protein S, vWF); two proteins being common (PAI-1, CD40LG)." (PMID 36203210, 2022). "Meanwhile, hypoglycemia induces several changes in the hemostatic parameters which include an increase in platelet aggregation, activation, degranulation as well as a rise in factor VIII and vWF levels." (PMID 33718455, 2021).
infective endocarditis (5 papers, 2019 to 2025). Infective endocarditis (IE) is an infection of the inner lining of the heart chambers (endocardium) and valves. "Infective endocarditis is regarded as a paradigm of bacterial diseases associated with vascular inflammation and VWF-interaction." (PMID 33015097, 2020). "Pathogenesis of bacterial infections, such as the infective endocarditis involves the enhanced secretion of VWF, which elicits crucial functions in platelet adhesion and thrombus formation at endothelial damage sites." (PMID 30972039, 2019). "Taking clinical symptoms into account, different functional aspects of the bacterial interaction with VWF can be directly or indirectly correlated with at least three severe infection diseases: infective endocarditis, bacterial sepsis, and cardiovascular complications." (PMID 33015097, 2020).
intracerebral hemorrhage (5 papers, 2016 to 2025). A cerebrovascular disorder characterized by bleeding into one or both cerebral hemispheres including the basal ganglia and the cerebral cortex. "A previous study has shown that VWF exhibits a protective role in pathological conditions, such as seizures, hypoxia and spontaneous intracerebral hemorrhage by promoting and modulating BBB flexibility and opening during disease states." (PMID 32321539, 2020). "Monitorization of the plasmin inhibitor complex, von Willebrand factor (VWF) levels, or fibrin/fibrinogen degradation products after r-tPA administration suggested that a test combining levels of these markers could aid in predicting intracerebral hemorrhages." (PMID 38103737, 2024).
myocardial ischemia (5 papers, 2013 to 2025). A disorder of cardiac function caused by insufficient blood flow to the muscle tissue of the heart. "Highly prothrombotic proteins, including von Willebrand factor and tissue factor, trigger platelet activation and coagulation cascade, further inducing local thrombus formation and homologous myocardial ischemia." (PMID 36698952, 2022). "Moreover, diltiazem also reduced myocardial ischemia, endothelia dysfunction and inflammatory responses, as indicated by changes in c-TnI, plasma vWF and ET-1 levels, as well as the myocardial protein expression levels of TNF-α and IL-6." (PMID 24137281, 2013).
ovarian carcinoma (5 papers, 2008 to 2024). A malignant neoplasm originating from the surface ovarian epithelium. "High levels of other pro-coagulants such as vWF, D-dimer, tissue plasminogen activator antigen, and reduced ATIII have been associated with poor disease prognosis in ovarian cancer." (PMID 39518024, 2024). "In conclusion, using a novel type of biotinylated recombinant antibodies that we call biobodies, we identified complement catabolitic products, EMILIN2, Von Willebrand factor and PEBP1 or a related protein, as candidate markers for ovarian carcinoma." (PMID 18652693, 2008). "Interestingly, DHA inhibited the development of ovarian cancer by downregulating phosphorylated focal adhesion kinase (pFAK), MMP-2, von willebrand factor (vWF) and macrophage infiltration." (PMID 33613116, 2021).
peritonitis (5 papers, 2016 to 2021). Inflammation of the peritoneum (tissue that lines the abdominal wall and covers most of the organs in the abdomen). "Indeed, VWF deficiency or blockade has been shown to reduce leukocyte recruitment in various murine models of inflammation, including cytokine-induced meningitis, wound healing, atherosclerosis, cutaneous inflammation, vasculitis, and peritonitis." (PMID 31921147, 2019).
respiratory failure (5 papers, 2020 to 2026). The significant impairment of gas exchange within the lungs resulting in hypoxia, hypercarbia, or both, to the extent that organ tissue perfusion is severely compromised. "Severe respiratory failure is characterized by diffuse pulmonary microvascular injury and produces marked increases in Factor VIII and vWF antigen in adults as well as in premature newborns." (PMID 32327998, 2020).
vascular tumors (5 papers, 2012 to 2026). "Immunohistochemical detection for vWF is widely used as a marker for endothelial differentiation in diagnostic pathology, particularly in vascular tumors such as AS." (PMID 40666093, 2025). "Immunohistochemically, vascular endothelial markers such as Von-Willebrand factor, CD34, CD31 and Fli-1 are commonly positive in most of tumors at varying intensities in each case, which help identify and diagnose the tumor as a type of vascular neoplasms." (PMID 24063649, 2013).
age-related macular degeneration (4 papers, 2018 to 2022). Age-related loss of vision in the central portion of the retina (macula), secondary to retinal degeneration. "We investigated the association between von Willebrand factor (VWF) and exudative age-related macular degeneration (AMD) in 114 Japanese patients." (PMID 29367644, 2018). "In other ocular diseases, elevated plasma VWF antigen levels have been reported in age-related macular degeneration, and multimeric VWF has been found in pachychoroid neovasculopathy." (PMID 36137144, 2022). "Previously, we demonstrated that VWF antigen levels decreased after intravitreal aflibercept injection in patients with age-related macular degeneration." (PMID 36137144, 2022).
alcoholic hepatitis (4 papers, 2015 to 2023). Acute hepatitis resulting from ingestion of alcohol. "A previous study reported that the VWF:Ag/ADAMTS13:AC in patients with severe alcoholic hepatitis was recovered in the recovery stage and worsened in the end stage compared with patients at the start of the treatment." (PMID 36829443, 2023). "Furthermore, patients with ALF and severe alcoholic hepatitis with a significant imbalance in the ADAMTS13 enzyme–VWF substrate had a higher mortality risk than those without the imbalance as well as LC." (PMID 36829443, 2023). "In patients with severe alcoholic hepatitis with or without cirrhosis, a negative association between ADAMTS-13, prothrombin time, and total serum bilirubin was observed, while VWF serum level was directly associated with disease severity." (PMID 37443746, 2023).
Arrhythmia (4 papers, 2018 to 2025). Any cardiac rhythm other than the normal sinus rhythm. "On the other hand, another study demonstrated that the concentrations of vWF were unrelated to postoperative AF, while intracardiac levels of IL-6 were associated with AF, emphasizing the heterogeneity and complexity of the inflammatory system in the development of cardiac arrhythmias." (PMID 41010936, 2025). "The potential role of endothelial damage, reflected by alterations in VWF levels, in the pathogenesis of cardiac arrhythmias was investigated on intracardiac specimens, specifically from the left atrial appendage (LAA), in patients undergoing CABG." (PMID 41010936, 2025). "Several studies have described an association between AF and abnormal circulating levels of prothrombotic plasma markers, such as fibrinogen, von Willebrand factor (vWF), and soluble P-selectin, suggesting that the arrhythmia itself contributes to the development of a pro-thrombotic state." (PMID 40299555, 2025). "In addition, several studies have described an association between AF and abnormal prothrombotic plasma markers, including fibrinogen, von Willebrand factor (vWF), and soluble P-selectin, suggesting that the arrhythmia itself contributes to the development of a pro-thrombotic state." (PMID 37959331, 2023). "Kaireviciute and collaborators demonstrated that elevated VWF expression in LAA tissue serves as a significant predictor of postoperative AF, underscoring the importance of tissue-specific expression of pathophysiologic markers in the development of postoperative arrhythmias." (PMID 41010936, 2025).
asthma (4 papers, 2014 to 2021). "In asthma patients treated with prednisolone, the von Willebrand factor and Plasminogen activator inhibitor-1 (PAI-1) were increased compared to healthy controls." (PMID 34440079, 2021). "Angiogenesis is a feature of airway remodeling in asthma, and it has been demonstrated that IL-33 can increase the expression of blood vessel von Willebrand factor (vWF), as well as angiogenic factors such as angiogenin when administered nasally to a murine asthma surrogate model." (PMID 31293586, 2019). "Although systemic fibrinolysis is impaired in patients with mild asthma, TATc levels in plasma were higher in healthy control subjects, while the systemic fold changes from baseline in TATc, ETP, vWF and PAI-1 are increased in the mild asthmatic group." (PMID 24502801, 2014).
bacteremia (4 papers, 2009 to 2025). "As bacteremia triggers complement activation meant to act as part of an innate immune response, it also results in unwanted endotheliopathy through endothelial cell dysfunction, resulting in increased cellular exocytosis of endothelial ultra-large von Willebrand factor (eULVWF) multimers." (PMID 41536402, 2025).
breast tumors (4 papers, 2021 to 2024). "VWF contributes to angiogenesis which enhances the dissemination of breast tumour cells to distal secondary sites." (PMID 33571850, 2021). "Presence of Snail1 in vWF-positive endothelial cells was detected in human breast tumors." (PMID 34335957, 2021). "•VWF plays an important role in breast tumour progression and metastasis." (PMID 33571850, 2021). "Similarly, elevated VWF levels correlated with increased breast tumour invasiveness." (PMID 33571850, 2021). "The results showed that MpEV-EPC exhibited the significantly upregulated expression of vWF, SNAIL, VE-Cadherin, FAP, and ALDH (TEC markers found in breast tumors) in comparison to nEV-EPC or the original EPC." (PMID 38515582, 2024). "The elevated levels of VWF have also been correlated with higher levels of the cancer antigen CA15–3, a breast tumour marker which is also raised in disseminated disease (p = 0.027)." (PMID 33571850, 2021). "Notably, the depletion of VWF did not affect the survival or outgrowth of the breast tumour cells in the absence of chemotherapy." (PMID 33571850, 2021).
cardioembolic stroke (4 papers, 2014 to 2022). "Furthermore, while cardioembolic strokes may have VWF-platelet rich structure in addition to a fibrin-rich core presumed to be due to the origin of the thrombus, this system is more directly applicable to thromboembolic stroke." (PMID 36558901, 2022). "An association between elevated levels of vWF and the NIHSS score on admission and poor clinical outcome has been demonstrated, although not for the cardioembolic stroke." (PMID 31701356, 2020).
central obesity (4 papers, 2012 to 2024). "It has been hypothesized that the mechanisms linking elevated levels of vWF/FVIII complex to insulin resistance and central obesity are related to the presence of underlying endothelial dysfunction and/or proinflammatory milieu even though this association is still controversial." (PMID 24278711, 2012). "The impairment of hemostatic balance identified in subjects with central obesity includes alterations of both intrinsic and extrinsic pathways with increased levels of factor VIII (FVIII) and von Willebrand factor (vWF), TF, FVII, and fibrinogen." (PMID 24278711, 2012).
cognitive decline (4 papers, 2018 to 2025). "This study aimed to investigate the relationship between plasma VWF levels and cognitive decline, as well as its association with brain atrophy as measured by structural MRI among older adults." (PMID 40969184, 2025). "Our results indicated that lower plasma VWF levels were associated with a faster rate of cognitive decline, as evidenced by scores on the MMSE and the CDR-SB." (PMID 40969184, 2025). "We observed that lower plasma VWF levels were associated with a faster rate of cognitive decline (MMSE: coefficient = 0.204, 95% CIs = [0.030, 0.378], p-value = 0.021; CDR-SB: coefficient = −0.268, 95% CIs = [−0.374, −0.163], p-value <0.001)." (PMID 40969184, 2025). "We found that lower plasma VWF levels were associated with a faster rate of cognitive decline, as measured by the MMSE and the CDR-SB." (PMID 40969184, 2025). "In conclusion, despite inconsistencies with prior studies, the observed association between lower VWF levels and faster cognitive decline, as well as specific patterns of brain atrophy, highlights the potential role of VWF in cognitive function and neurodegeneration." (PMID 40969184, 2025). "Therefore, the relationship between blood VWF levels and cognitive decline over time remains inconclusive, highlighting the need for further research in this area." (PMID 40969184, 2025).
epithelioid angiosarcoma (4 papers, 2013 to 2024). "Immunoreactivity for endothelial markers, such as CD31, erythroblast transformation-specific-related gene (ERG), and von Willebrand factor (vWF) helps to differentiate epithelioid angiosarcoma from epithelioid sarcoma." (PMID 33520482, 2020). "Additionally, CD31 and von Willebrand factor antibodies are helpful in cases of epithelioid angiosarcoma, since it can mimic a poorly differentiated carcinoma on histological investigations." (PMID 38291481, 2024).
factor deficiency (4 papers, 2024 to 2025). "In recent years an acquired von Willebrand factor deficiency has been added to the syndrome definition, a deficiency that occurs through the loss of large multimeric von Willebrand factor multimeric molecules." (PMID 40283648, 2025). "Shear stress from a narrowed aortic valve degrades von Willebrand factor multimers, leading to angiodysplasia formation and von Willebrand factor deficiency." (PMID 39456826, 2024).
Glanzmann thrombasthenia (4 papers, 2013 to 2025). "Occasionally, these antibodies interfere with fibrinogen binding to platelet GPIIb/IIIa or von Willebrand factor (vWF) binding to GPIb/IX receptors, resulting in severe bleeding phenotypes from acquired Glanzmann’s thrombasthenia or Bernard–Soulier syndrome, respectively." (PMID 39590303, 2024).